Y_RNA (Y RNA )
Gene: Miscellaneous RNA gene on chromosome 7 (77,013,583 to 77,013,684, forward strand). Ensembl gene ENSG00000201885.
Homologues: Orthologues: chimpanzee Y_RNA (99% identical), pig Y_RNA (75% identical). Paralogues in human: Y_RNA (100% identical), Y_RNA (97% identical), Y_RNA (93% identical), Y_RNA (92% identical), Y_RNA (90% identical), Y_RNA (89% identical), Y_RNA (87% identical), Y_RNA (85% identical), RNY3 (84% identical), RNY3P12 (84% identical), Y_RNA (84% identical), RNY3P1 (83% identical), and 98 more.